BCHE (butyrylcholinesterase)
Diseases named in the same sentence as BCHE in open-access papers (continued):
Sharing a sentence is not in itself a finding about the gene and the disease.
Alzheimer disease (continued). "It is reported that quercetin as well as some polyphenolic-rich extracts inhibit the enzymes anticholinesterase (AChE) and butyrylcholinesterase (BChE), thus improving cognitive abilities in Alzheimer’s disease, supporting a neuroprotective role of polyphenols." (PMID 31861633, 2019). "Then, the inhibitory ability of samples was investigated against α-amylase and α-glucosidase enzymes involved in diabetes and against acetylcholinesterase and butyrylcholinesterase enzymes considered as strategy for the treatment of Parkinson’s or Alzheimer’s diseases." (PMID 31382601, 2019). "Butyrylcholinesterase (BChE) plays an important role in the progression of the Alzheimer’s disease." (PMID 31347933, 2019). "Besides, harmine was considered to be a potential candidate for Alzheimer’s disease therapy by inhibiting acetylcholinesterase (AChE) and butyrylcholinesterase (BChE) activity." (PMID 29534494, 2018). "Furthermore, in the late stage of Alzheimer’s disease, the level of AChE was found to drop to 55–67% of normal value, while BChE activity increases up to 120%." (PMID 29463056, 2018). "As Ceylon cinnamon bark and leaf demonstrated both AChE and BChE inhibitory activities consumption in daily life could increase the acetylcholine level and would be beneficial for management of Alzheimer's disease." (PMID 28951761, 2017). "DL0410, containing biphenyl and piperidine skeletons, was identified as an acetylcholinesterase (AChE) and butyrylcholinesterase (BuChE) inhibitor through high-throughput screening assays, and further studies affirmed its efficacy and safety for Alzheimer’s disease treatment." (PMID 28933746, 2017). "Therefore, currently BChE inhibitors such as cymserine analogues and the dual inhibitor of both AChE and BChE such as rivastigmine are used therapeutically for treating Alzheimer's disease and other related dementias." (PMID 28951761, 2017). "Indeed, both acetylcholinesterase and butyrylcholinesterase inhibitors have been key targets for the treatment of neurodegenerative disorders such as Alzheimer's disease." (PMID 26798334, 2015). "Tacrine (1,2,3,4-tetrahydroacridin-9-amine) is another synthetic drug which easily crosses the blood brain barrier and is used as a highly effective drug for ameliorating Alzheimer disease manifestation by inhibition AChE and by lower but still effective inhibition of BChE." (PMID 24893223, 2014). "AChE and BChE are enzymes that degrade the neurontransmitter acetylcholine through hydrolysis and lead to Alzheimer’s disease; hence, such diseases might be prevented by inhibition of AChE and BChE." (PMID 22890173, 2012). "BChE is likely to be involved in neurodegenerative disorders such as Alzheimer's disease." (PMID 21569551, 2011). "It would be instructive to study the prevalence and course of both insulin resistance and Alzheimer's disease in these individuals who may be considered to be on butyrylcholinesterase inhibitors." (PMID 17096857, 2006). "Butyrylcholinesterase and acetylcholinesterase related proteins were found common to both Alzheimer's disease and diabetes; they may play an etiological role via influencing insulin resistance and lipid metabolism." (PMID 17096857, 2006). "While AchE levels are reduced early in Alzheimer's disease, BchE levels rise with disease; selective BchE inhibition may be useful to ameliorate cholinergic defect." (PMID 17096857, 2006). "The results indicated that the methanol extract of Hypericum perforatum demonstrated a potent inhibition of both acetylcholinesterase and butyrylcholinesterase, suggesting that it could potentially be used as a therapeutic agent in neurodegenerative conditions such as Alzheimer’s disease." (PMID 40573869, 2025).
Alzheimer disease (continued). "Alzheimer’s disease (AD) is a progressive neurodegenerative disorder marked by pathological features such as tau protein aggregation and hyperphosphorylation, chronic neuroinflammation, and cholinergic dysfunction mediated by acetylcholinesterase (AChE) and butyrylcholinesterase (BuChE)." (PMID 41045341, 2025). "In addition, the capacity of nanoparticles to inhibit AChE and BChE shows that AC-AgNPs could be used to manage Alzheimer’s disease." (PMID 36903556, 2023). "Similarly, the phenolic and flavonoid contents of Elatostema papillosum showed significant antioxidant and inhibitory activity against AChE and butyrylcholinesterase (BChE) in Alzheimer’s disease, with IC50 values of 165.40 4.01 and 213.81 3.57 μg/mL, respectively." (PMID 36986610, 2023). "The promising AChE and BChE inhibitory capabilities of our synthesised chromium oxide nanoparticles implies that such NPs could be used therapeutically in neurodegenerative illnesses, including Alzheimer’s disease." (PMID 36313367, 2022). "Two enzymes, acetylcholinesterase (AChE) and butyrylcholinesterase (BChE), are involved in the of acetylcholine hydrolysis, decreasing its level in Alzheimer’s disease, and thus, prohibition of both enzymes is a well-established strategy for the alleviation of Alzheimer’s disease." (PMID 36295014, 2022). "Acetylcholinesterase (AChE) and butyrylcholinesterase (BChE) are largely involved in the neural transmission of synapses and their inhibitors have been identified as targets in the treatment of neurodegenerative disorders, including Alzheimer’s diseases and myasthenia gravis." (PMID 34018093, 2021). "Compounds 230 and 235 inhibited the butyrylcholinesterase (BChE) more potently than neostigmine, suggesting that they may serve as lead compounds for the development of novel BChE inhibitors and candidate lead compounds for the prevention or treatment of Alzheimer’s disease." (PMID 32858984, 2020). "However, the inhibition of BChE is considered a potential therapeutic target to restore the levels of ACh in the brain, improving cognitive deterioration and reducing the adverse effects in patients with Alzheimer’s disease." (PMID 31731417, 2019). "Furthermore, both essential oils were tested to evaluate their inhibitory activity on acetylcholinesterase (AChE) and butyrylcholinesterase (BChE), two enzymes important as pharmacological targets in the design of drugs active against neurodegenerative diseases such as Alzheimer’s disease." (PMID 31731807, 2019). "The development of selective butyrylcholinesterase (BChE) inhibitors may improve the treatment of Alzheimer’s disease by increasing lower synaptic levels of the neurotransmitter acetylcholine, which is hydrolysed by acetylcholinesterase, as well as by overexpressed BChE." (PMID 31382668, 2019). "The cholinergic concept of Alzheimer’s disease (AD) was initially resulted from postmortem studies of the brain, which ultimately led to the development of new drugs based on the inhibition of the key enzymes acetylcholinesterase (AChE) and butyrylcholinesterase (BChE)." (PMID 26530857, 2015). "Therefore, inhibition of BChE by using G. Cambogia will not only produce better cholinergic transmission but also has the potential to interfere with the disease process in Alzheimer's disease and other dementing disorders." (PMID 21569551, 2011). "Therefore BchE may have a role in coregulating local concentrations of acetylcholinesterase in Alzheimer's disease." (PMID 17096857, 2006). "The methanol extract also exhibited moderate inhibition of butyrylcholinesterase (BChE), with an IC50 of 122 μg/mL, suggesting possible applications in Alzheimer’s disease therapy." (PMID 39942760, 2025).
Alzheimer disease (continued). "Likewise, for the enzyme inhibition tests, the IC50 values for cholinesterase inhibition (AChE and BCHE) were close to those of the reference compound, galantamine, which served as the positive control since it is clinically applied in the management of mild Alzheimer’s disease." (PMID 41451025, 2025). "Two neurotransmitter-degrading enzymes (AChE and BChE) and the β-amyloid formation enzyme (BACE-1) were investigated to control Alzheimer’s disease." (PMID 38231711, 2023). "Further, isolated five lignans from the heartwood of T. baccata and demonstrated their positive role in inhibiting butyrylcholinesterase (BChE) and lipoxygenase (LOX) activities, which play a role in the pathogenesis of Alzheimer’s disease." (PMID 37107262, 2023). "Acetylcholinesterase (AChE), butyrylcholinesterase (BChE), and β-secretase (BACE-1) are the key enzymes involved in controlling Alzheimer’s disease (AD) pathology." (PMID 33924574, 2021). "The acetylcholinesterase (AChE) and butyrylcholinesterase (BChE) inhibitory effects of ME and HWE were moderate and comparable with galanthamine, the standard drug to treat early stages of Alzheimer’s disease (AD)." (PMID 27196881, 2016). "Inhibition of AChE and BChE are the key enzymes in the breakdown of acetylcholine and butyrylcholine that may be considered as one of the treatment approaches against several neurological disorders such as Alzheimer’s disease, senile dementia, ataxia, and myasthenia gravis." (PMID 25889712, 2015). "Moreover, analysis of serum BChE activity in experimentally developed obesity and demonstrate the mechanisms that link obesity with altered brain function and propose future directions to be taken for addressing obesity oxidative stress and Alzheimer's disease." (PMID 21569551, 2011). "C1a reversibly inhibits AChE and BChE without undesirable peripheral effects, making it a promising candidate for the treatment of Alzheimer’s disease." (PMID 39201735, 2024). "Likewise, DL strongly inhibited cholinergic (AChE and BChE) and β-amyloid formation enzymes (BACE-1), thereby showing potential as an effective agent to control Alzheimer’s disease." (PMID 38066118, 2023). "Inhibitory activities against the key enzymes relevant to obesity (lipase), diabetes (α-glucosidase and α-amylase), and Alzheimer’s disease (AChE, BChE, and BACE-1) and the nonenzymatic glycation reaction were also assessed." (PMID 35161275, 2022). "In fact, it has been reported that AchE activity is reduced by 67% compared to the normal level in the hippocampus and temporal lobe during the progression of Alzheimer’s disease while the BchE activity is gone up to 165%, relative to normal levels." (PMID 34679706, 2021). "Butyrylcholinesterase (BChE) is a non-specific enzyme with clinical pharmacological and toxicological significance, which was a renewed interest as therapeutic target in Alzheimer's disease (AD) nowadays." (PMID 33195011, 2020). "The inhibition of butyrylcholinesterase (BChE) was more marked, with a value of 3.50 ± 0.05 mg GALAE/particles, highlighting a potential efficacy of NVs in the more advanced stages of neurodegenerative diseases, such as Alzheimer’s disease, where BChE activity tends to increase." (PMID 41304917, 2025). "In our previous work concerning natural anti-Alzheimer’s disease (anti-AD) drugs from marine sources, eckol from Ecklonia stolonifera showed selective inhibition of acetylcholinesterase (AChE) and β-site amyloid precursor protein-cleaving enzyme 1 (BACE1), but not butyrylcholinesterase (BChE)." (PMID 30744179, 2019).
diabetes (78 papers, 2005 to 2025). "This association underscores the role of BChE as both a regulator and responder in metabolic processes that potentially influence obesity, diabetes, and related diseases." (PMID 40116876, 2025). "Increased plasma BChE activity observed in SHR+DM suggests a potential involvement of this enzyme in the pathophysiology of concomitant diabetes and hypertension, possibly through its association with lipid metabolism." (PMID 40698664, 2025). "As for prospective cohort studies, serum BChE increased the risk of incident diabetes among Japanese men, and the risk of incident dyslipidemia in participants in a medical check-up center." (PMID 37138337, 2023). "Multivariate logistic regression analysis with adjustment for the prevalence of diabetes mellitus (the main BMS-ISR clinical risk factor) confirmed that the rs1803274 polymorphism of BCHE was significantly associated with the prevalence of ISR." (PMID 26497592, 2015). "The extract exhibited significant inhibitory effects on enzymes linked to diabetes mellitus (α-amylase and α-glucosidase) and neurodegenerative diseases (acetylcholinesterase and butyrylcholinesterase), suggesting potential therapeutic applications in managing metabolic and cognitive disorders." (PMID 40006842, 2025). "Several clinical observations have suggested that BChE may play a role in altered lipoprotein metabolism in hypertriglyceridemia associated with insulin resistance or insulin deficiency in type 2 diabetes mellitus (DM)." (PMID 40698664, 2025). "There was no significant independent association of POD with the preoperative BChE activity (OR = 0.971 (95% CI: 0.939 to 1.004), p = 0.086), age (OR = 1.027 (95%CI: 0.998 to 1.057), p = 0.065) or type 2 diabetes mellitus (OR = 1.508 (95%CI: 0.800 to 2.842), p = 0.204)." (PMID 38424490, 2024). "Furthermore, several studies demonstrated an association between BChE activity and metabolic risk factors (such as obesity, hyperlipidemia and diabetes)." (PMID 37941017, 2023). "They proposed BMI as an independent risk factor for higher BChE activity in young men and glucose as an independent risk factor for higher BChE activity in women, which shows that changes in BChE activity may be a predictor of diabetes." (PMID 29780825, 2018). "Given that delayed loop ileostomy reversal often involves patients with significant comorbidities or complications post-initial surgery, such as diabetes or renal failure, preoperative BChE levels could be used to identify high-risk patients who may require more intensive perioperative care." (PMID 39424880, 2024). "In this study, we sought to build upon these findings by analyzing BChE in an animal model of diabetic hypertension, as hypertension is a common comorbidity in patients with diabetes." (PMID 40698664, 2025). "T. terrestris extracts, particularly ethanol extracts, have been shown to have a substantial inhibitory effect against α-glycosidase and cholinesterases (AChE and BChE), which are essential for managing diabetes and Alzheimer’s disease, respectively." (PMID 41465738, 2025). "A study on the effects of aqueous extract of S. macrocarpon on cholinesterase activity in alloxan-induced diabetes showed a significant increase in AChE and BChE in diabetic rats." (PMID 40430525, 2025). "Plasma BChE activity was measured in 844 humans (554 women) of the cross‐sectional Tübingen Diabetes Family Study, with a wide BMI range (17.7–55.1 kg/m2)." (PMID 40243328, 2025). "Here, we investigated plasma BChE activity in a rat model of comorbid hypertension and type 1 diabetes mellitus (DM) induced by a single injection of streptozotocin (STZ, 55 mg/kg) in male spontaneously hypertensive rats (SHR) (SHR+DM)." (PMID 40698664, 2025). "Multivariable analysis including either preoperative or postoperative BChE activity as well as age, MoCA, type 2 diabetes mellitus, coronary heart disease, type of surgery and intraoperative administration of red-cell concentrates was performed." (PMID 38424490, 2024).
diabetes (continued). "The enzyme inhibition assays further underscored the therapeutic potential of these extracts, with significant inhibitory effects on enzymes related to neurodegenerative diseases (AChE, BChE), diabetes (amylase, glucosidase) and skin pigmentation (tyrosinase)." (PMID 39765854, 2024). "Key clinical enzymes involved in neurodegenerative diseases AChE and BChE, diabetes (α-amylase and α-glucosidase) and skin whitening (tyrosinase) were also assayed." (PMID 36770677, 2023). "The finding of the current research work shows the devastating AChE, BChE, α-amylase, and α-glucosidase potentials of these compounds and reveals their central role in AD and diabetes." (PMID 35942378, 2022). "Considering complications related to diabetes, other clinical enzymes, namely, acetylcholinesterase (AChE), butyrylcholinesterase (BChE), tyrosinase, elastase and pancreatic lipase, were used." (PMID 35335362, 2022). "This flavonoid was responsible for the antioxidant activities and inhibitory activities against the key enzymes controlling diabetes (α-glucosidase and α-amylase) and AD (AChE, BChE, and BACE-1)." (PMID 32887386, 2020). "So far, the studies concerning the activity of BChE in humans have included patients with hyperlipidemia, diabetes, or cardiovascular disease." (PMID 29780825, 2018). "PD patients usually have a number of comorbidities and BChE activity is reportedly related to many pathologies, including hepatic function and metabolic syndrome (diabetes mellitus, hypercholesterolemia, TC, and TG)." (PMID 28840123, 2017). "Serum activity of the BChE are affected by dietary fat, obesity, hyperlipidemia and diabetes mellitus." (PMID 21569551, 2011). "Here we (a) studied the level of BChE among persons with diabetes mellitus (b) constructed the phylogenetic tree of 25 BChE genes from publicly available sequence data." (PMID 16150144, 2005). "The stronger inhibitory effect on BChE suggests a potential role in the treatment of neurodegenerative diseases, while the inhibition of α‐glucosidase supports its potential application in managing metabolic disorders such as diabetes." (PMID 40351366, 2025). "The detected link between BChE and insulin resistance in our study is consistent with the results of smaller studies involving patients with and without overt diabetes, where BChE activity was found to be negatively associated with insulin sensitivity." (PMID 40243328, 2025). "Depsidones could have the potential as lead metabolites for neurodegenerative illnesses and diabetes through their inhibition of butyrylcholinesterase, tyrosinase, α-glucosidase, and acetylcholinesterase enzymes." (PMID 37197584, 2023). "Furthermore, in vitro assays have been used to assess the sample inhibitory activities on enzymes involved in diabetes (i.e., α-amylase and α-glucosidase) and neurodegenerative diseases (acetylcholinesterase and butyrylcholinesterase)." (PMID 32024045, 2020). "For patients treated with VA-ECMO for postcardiotomy shock, age, gender (female), diabetes, preoperative renal insufficiency, obesity, serum butyrylcholinesterase, mean lactate concentration, lactate clearance, and logistic EuroSCORE are factors reported to be associated with poor outcome." (PMID 32252267, 2020). "BChE levels are decreased in disorders such as severe liver disease, poisoning with organophosphate compounds, cancer, and cachexia, whereas increased levels of BChE have been reported in obesity, diabetes mellitus, uremia, hyperthyroidism, and hyperlipidemia." (PMID 29736152, 2018). "Also it was shown that interaction of butyrylcholinesterase (BChE K) and apolipoprotein E (ApoE) was associated significantly with CAD and diabetes." (PMID 26587547, 2015). "BChE activity could also be used to select the drug for treatment of hypertriglyceridaemia in type 2 diabetes mellitus." (PMID 16150144, 2005).